S100A12 (S100 calcium binding protein A12)
Diseases named in the same sentence as S100A12 in open-access papers (continued):
Sharing a sentence is not in itself a finding about the gene and the disease.
vitiligo (1 paper, 2022). Generalized well circumscribed patches of leukoderma that are generally distributed over symmetric body locations and is due to autoimmune destruction of melanocytes. "S100A9 and S100A12, the two alarmins are prone to rise after oxidative stress which is an important inducer for vitiligo initiation, and then involved in the aberrant immune response." (PMID 36569840, 2022). "Therefore, in this study we would like to detect the serum expression of these alarmins (HMGB1, S100B, IL-1α, IL-33, S100A9, and S100A12) in NSV patients and healthy controls, to further investigate their clinical significance in the diagnosis and assessment of disease activity/severity in vitiligo." (PMID 36569840, 2022).
infection (46 papers, 2008 to 2026). The state of being infected such as from the introduction of a foreign agent such as serum, vaccine, antigenic substance or organism. "Of course, we cannot exclude other ways that pathogenic microbe-induced infection results in the secretion of S100A12 in CAP patients." (PMID 34745092, 2021). "It is possible that the infection of Streptococcus pneumoniae, pathogenic bacteria, pathogens infection, or other pathogenic bacteria, activated the immune system and evoked the elevation of neutrophils and production of S100A12 in human bodies." (PMID 34745092, 2021). "In this study, S100A12 was associated with a protective response to M. leprae colonization/infection in HCs." (PMID 32849645, 2020). "However, infection with E. granulosus results in a more granulomatous type of inflammation although other cells were also shown to express S100A12 at the site of infection-associated inflammation." (PMID 29665827, 2018). "Also, experimental infection in cattle with Echinococcus granulosus was associated with a strong S100A12 response." (PMID 29665827, 2018). "However, the association between fecal score and fecal S100A12 concentrations could also reflect an infection with another enteropathogen or enteropathogens for which puppies in this study were not evaluated." (PMID 29665827, 2018). "Antimicrobial protein S100A12 sequesters Zn(II) via a His3Asp motif to inhibit pathogens during infection." (PMID 40970396, 2025). "Here, UV-vis and NMR spectroscopies and molecular dynamics (MD) simulations are used to gain molecular insight into the Zn(II) chelation properties of S100A12 under pH conditions relevant to infection and inflammation." (PMID 40970396, 2025). "Apart from playing a vital role in human health and diseases, S100A8, S100A9, and S100A12 proteins are closely related to the infection (including bacteria, viruses, and parasites) process in pigs." (PMID 38256103, 2024). "To address the current lack of reliable and timely detection tools for porcine S100A8, S100A9, and S100A12 proteins during the infection process, we generated mAbs specific to these three proteins in this study using hybridoma technology." (PMID 38256103, 2024). "The higher expression of FTH1, ISG15, SRGN and S100A12 genes observed in infected animals suggests the activation of the host immune system to resist the infection." (PMID 37761803, 2023). "S100A12 belongs to the S100 family, and its protein products are of great significance in anti-infection, tumor cell proliferation, migration and other processes." (PMID 36479092, 2022). "It was evident that S100A12 expression was significantly elevated in the uncomplicated infection group compared to healthy controls (p = 1.95e-8), where 11 of the 12 patients had higher S100A12 expression than the highest value in the control group." (PMID 34108608, 2021). "In the current study, it has been demonstrated that S100A12 expression in the whole blood is a robust marker for severe infection and severe respiratory viral infection." (PMID 34108608, 2021). "In our previous works on host response to infection, we proposed several genes as the signature for bacterial infection, among which S100A12 was the most prominent marker." (PMID 34108608, 2021). "The exact role of S100A12 in the response to severe infection will require more in-depth investigation." (PMID 34108608, 2021). "Under physiological conditions, there is sufficient storage of S100A12 in neutrophils and myeloid cells, while S100A12 is significantly elevated during trauma, infection, heat, stress, and many other inflammatory diseases." (PMID 34745092, 2021). "It was evident that S100A12 expression was significantly elevated in the septic group compared to the cardiogenic shock group at the first time point (p = 2.99e-7), again validating S100A12 as a marker for infection." (PMID 34108608, 2021). "The S100A12 levels were also elevated in patients with systemic JIA compared to patients with infection and HCs." (PMID 33224145, 2020).
infection (continued). "The sensitivity and specificity of S100A12 for distinguishing between infection and systemic JIA were 66 and 94%, respectively." (PMID 33224145, 2020). "The expression of S100A12 in patients with RR, able to restrict the infection but with concomitant nerve damage, suggests that like many antimicrobial peptides, the antimicrobial and inflammatory functions of these molecules are linked." (PMID 27355424, 2016). "This suggests that the expression of S100A12 protein was greatest at the site of disease in patients that are able to limit the infection." (PMID 27355424, 2016). "It has been reported that there is 5.2 fold to 49.1 fold up-regulation of S100A12 expression for three cows at the infection dose of 1 × 105 S." (PMID 25273983, 2014). "Expression of the S100A12 gene was up-regulated in the spleen and blood during infection with Haemophilus parasuis (HPS), porcine circovirus type 2 (PCV2), or after stimulation with lipopolysaccharides (LPS) or Poly I: C." (PMID 25110868, 2014). "At 30 hpi, MEC express genes encoding different acute phase proteins, including SAA3, SERPINA1 and PTX3 and factors, such as S100A12, that contribute directly to fighting the infection." (PMID 24521038, 2014). "Our previous studies indicated that the S100A12 gene was abundant in the immune tissues of pigs and was significantly upregulated during infection with Haemophilus parasuis (HPS) or porcine circovirus type 2 (PCV2)." (PMID 25110868, 2014). "S100A12 was present in milk samples from S. aureus-infected udder quarters and the level of the protein was dependent on the severity of infection." (PMID 18513449, 2008). "Moreover, the gene S100A12 was involved in major immune-related GO terms identified across time points post-infection (H7 vs. H21 and L7 vs. L21)." (PMID 36902251, 2023). "S100A8 and S100A12 are among the most highly expressed genes on average throughout infection." (PMID 35019713, 2022). "Infection-induced inflammation is one of the primary resources for S100A12 production." (PMID 34745092, 2021). "Because the host deploys multiple metal-withholding proteins that coordinate various metal ions (e.g., CP, lactoferrin, siderocalin, and S100A12) at infection sites, bacterial pathogens must respond to the concerted limitation of multiple metal nutrients to cause infection." (PMID 34549997, 2021). "- independent of their number or subspecies - as well as an infection with the viral pathogens CCV or CPV2 were shown to be associated with alterations in fecal S100A12 concentrations on univariate analysis but not in a multivariate model." (PMID 29665827, 2018). "Here, we hypothesized that S100A12 via its antimicrobial activity contributes to host defense against infection by mycobacteria in humans." (PMID 27355424, 2016). "Furthermore, significantly increased S100A12 protein expression was detected in the milk whey from the infected udders in all three cows at 16 h post-infection." (PMID 25273983, 2014). "Similarly, other genes associated with the mammary gland response to infection are expressed at higher levels in SA24T0, e.g. S100A8, S100A12, CXCL10, interleukin (IL) 1B and lactotransferrin (LTF)." (PMID 23324411, 2013). "Indeed, lowering the stringency of the microarray analysis allowed the identification of over 70 genes, including several genes known to be associated with the mammary gland response to infection, e.g. SOD2, IL1B, LTF, S100A8 and S100A12." (PMID 23324411, 2013). "This novel finding suggests that S100A12 may have a direct role in protecting mammary tissue from infection by coliform bacteria and may play a role in protecting newborn suckling calves from bacterial infections." (PMID 18513449, 2008). "Significantly increased S100A12 protein expression (P < 0.01) was detected in the milk whey from the infected udders in all three cows relative to their respective intramammary control quarters (at 16 h post-infection)." (PMID 18513449, 2008).
infection (continued). "Cow 1419 had a concentration of 420 ng/ml of S100A12 in milk from the control udder at 16 h post-infection while the S100A12 levels in the udders that had been challenged with 1 × 105 and 1 × 106 bacteria were almost five times greater (1920 ng/ml in the milk from both udder quarters) (P < 0.01)." (PMID 18513449, 2008). "Moreover, there was a relatively small but significantly (P < 0.01) higher level of S100A12 in milk from the control udder quarters 16 h post-infection compared with the corresponding pre-infection samples." (PMID 18513449, 2008). "Interestingly, using an antigen capture ELISA it was demonstrated that S100A12 levels in milk samples from the control udder quarters at 16 h post-infection showed a small but significant increase compared to the pre-infection control samples." (PMID 18513449, 2008). "At the common infection dose of 1 × 105 bacteria for cows 1419, 1490 and 1592, there was 5.2, 36.5 and 49.1 fold up-regulation of S100A12 expression and 11.1, 9.9 and 19 fold up-regulation of PTX3 expression, compared to the intra-animal controls, respectively (all P < 0.01)." (PMID 18513449, 2008). "Moreover, by interpreting the decision patterns of our classification system, we identified that different immune cells upregulating or downregulating the expression of the genes CD3, CD14, CD16, FOSB, S100A12, and TCRɣδ can accurately differentiate between different degrees of infection." (PMID 38892107, 2024). "Thus, S100A12 expression is a clear indicator of severe infection." (PMID 34108608, 2021). "However, the relationship between mortality due to infection and S100A12 should be considered." (PMID 23324110, 2013). "The results of serum sample testing showed that these mAbs specifically identified the proteins S100A8, S100A9 and S100A12 in the serum and were able to evaluate changes in the protein content of S100A8, S100A9, and S100A12 during infection." (PMID 38256103, 2024). "However, since the biological activities of S100A8, S100A9, and S100A12 proteins are affected by redox conditions, pH, metabolite, and nutrient distribution at the site of infection, it is unclear whether the changes in protein expression are consistent with their biological activities yet." (PMID 38256103, 2024). "Based on the literature available, we hypothesized that infections with enteric parasites - but not enteropathogenic viruses - are associated with increased fecal canine S100A12 concentrations, and that these etiologies need to be ruled out when using fecal S100A12 as a biomarker in dogs with IBD." (PMID 29665827, 2018). "Thus, infections with enteropathogens evaluated in this study are not primarily associated with alterations in fecal S100A12 concentrations, whereas the concentration of fecal S100A12 is affected by the fecal score which reflects the overall health of the digestive tract." (PMID 29665827, 2018). "Congruent with the research above, gastric mucosa infected with H. pylori exhibited abundant S100A12 when compared to noninfected tissue, localizing primarily to polymorphonuclear cells in response to infection." (PMID 32184815, 2020). "This study showed that fecal S100A12 concentrations in puppies are not affected by an infection with Toxocara canis or Giardia sp." (PMID 29665827, 2018). "Since S100A12 and PTX3 display microbial growth inhibition and binding properties, respectively, they could provide a new class of natural anti-microbial agents that could assist defense of the mammary gland against chronic and subclinical infections." (PMID 18513449, 2008). "Next, 109,584 cells from 4 non-human primates at 10 weeks after infection with MTB6 were used to observe the expression of two genes, S100A12 and S100A8." (PMID 40415930, 2025). "All other markers (CCL4, IL-1Ra, TNF, S100A12, ferritin, C1q, CRP, and ApoA1) yielded no or hardly any detectable signals or failed to discriminate before and after infection (ApoA1, C1q)." (PMID 34943175, 2021).
infection (continued). "However, CP is not the only zinc binding protein found at sites of infection, with humans producing both S100A7, secreted by keratinocytes, and S100A12, secreted by neutrophils, as well as other unidentified mechanisms for restricting zinc availability." (PMID 40463161, 2025).
tumor (42 papers, 2014 to 2025). "Other members of the S100 family, such as S100A12, have also been associated with a tumor inflammation signature." (PMID 38892279, 2024). "S100A12 is closely related to vascular invasion by tumor cells, and causes excessive inflammation and vascular invasion, which lead to tumor recurrence and metastasis." (PMID 34122500, 2021). "The S100A12 gene expression was associated with the tumor stage in ESCC patients." (PMID 33859939, 2021). "In addition, upregulation of S100A12 was significantly associated with tumor size, tumor-node-metastasis (TNM) stage and lymph node metastasis (LNM)." (PMID 32015423, 2020). "RT-qPCR and Western blot analyses confirmed that CTHRC1, APOD, and S100A12 expression was significantly upregulated in the tumor group, while ASCL2 expression was significantly downregulated." (PMID 40898459, 2025). "Reverse transcription quantitative polymerase chain reaction and Western blot analyses confirmed that CTHRC1, APOD, and S100A12 were significantly upregulated in the tumor group, whereas ASCL2 expression was significantly downregulated." (PMID 40898459, 2025). "Future research is needed to determine potentials of S100A12 as a tumor marker or therapeutic target." (PMID 40072746, 2025). "Human S100A12 is significantly overexpressed in the inflammatory compartment, and elevated serum levels of S100A12 are observed in patients with various inflammatory, neurodegenerative, metabolic, and neoplastic diseases." (PMID 37744382, 2023). "In contrast, LL-37, ARG1, PGLYRP1 and S100A12 also exhibit antitumor activity affecting tumor cells directly or through the modulation of specific immune and nonimmune stromal cell populations." (PMID 36230605, 2022). "Numbers of S100A8/A9+ and S100A12+ cells were highly correlated in tissues of UC dogs (ρ = 0.96, P < 0.0001) and in dogs with non-neoplastic disease (ρ = 0.94, P = 0.0048)." (PMID 36411489, 2022). "Silencing S100A12 reduced the aggressive growth of tumor cells with either in vitro or in vivo experiments." (PMID 34475990, 2021). "Upon univariate analysis, hazards ratios for having a tumor with low S100A12 expression were 1.82, 2.51 and 1.85 for PFS, DSS and OS respectively, while the corresponding figures for low HLA class I expression were 2.31, 3.32 and 2.34." (PMID 33469045, 2021). "In the multivariate analysis, S100A12 and HLA class I were analyzed with sex, age, tumor size and nodal status as covariates." (PMID 33469045, 2021). "Further, S100A12 expression is strikingly increased in PTC and strongly associated with TNM stage, tumor size, and lymph node metastasis." (PMID 34475990, 2021). "Compared with para-cancer tissues, the expression levels of S100A4/S100A6/S100A10/S100A11/S100A13/S100A14/S100P were higher in HCC tissues, while the expression levels of S100A8/S100A9/S100A12 were decreased in tumor tissues." (PMID 33815482, 2021). "To further investigate the mechanism underlying the effect of S100A12 shRNA treatment in the xenograft mouse model, we analyzed tumor growth by H&E staining and examined S100A12 and Ki67 expression in tumor sections by IHC." (PMID 32015423, 2020). "An in vivo study also showed that silencing S100A12 dramatically suppressed tumor cell growth and decreased Ki67 expression in a xenograft mouse model." (PMID 32015423, 2020). "Overexpression of S100A12 was significantly correlated to the tumor size (*P < 0.05), tumor TNM stage (*P < 0.05) and lymph node metastasis (*P < 0.05)." (PMID 32015423, 2020). "The in vivo study also found that silencing S100A12 reduced the aggressive growth of tumor cells in xenografted mice." (PMID 32015423, 2020). "The network associated with regulation of tissue invasion by tumor cell lines and lipid export was connected by five proteins: ACAT1, CAV1, CTSS, S100A12, and S100A9." (PMID 33607292, 2020).